MDM2 (MDM2 proto-oncogene)
Diseases named in the same sentence as MDM2 in open-access papers (continued):
Sharing a sentence is not in itself a finding about the gene and the disease.
tumor (continued). "Indeed, a tumor-derived 10-48 GBM cell line, showed similarly high levels of MDM2 using quantitative digital PCR (cn=88)." (PMID 26328271, 2015). "We have found that JapA effectively inhibits the tumor growth and the protein expression of MDM2 and NFAT1 in vivo, without inducing any apparent host toxicity." (PMID 26461225, 2015). "The tumor stained negatively for desmin, S-100, c-Kit, CK-AE1/AE3, CDK4 and MDM2." (PMID 26337721, 2015). "Fluorescence in situ hybridization showed that the tumor cells did not have the DDIT3 alteration or amplification of MDM2." (PMID 25621027, 2015). "SNP 309 status also did not consistently correlate with overall levels of MDM2 expression either by array-based analysis or in a small validation cohort of tumor RNA samples using qPCR." (PMID 26378811, 2015). "Thus, in non-tumor cells, PNC27 enters the cell, but in cancer cells it is retained in the membrane due to its affinity for mdm-2, and forms pores." (PMID 24885242, 2014).
tumor (continued). "Q-PCR of the tumor specimens revealed varying levels of MDM2 and CDK4 amplification, with 44 cases (91.7%) and 46 cases (95.8%) showing positive amplification of CDK4 and MDM2 genes, respectively." (PMID 25121597, 2014). "MDM2 amplification and the fusion transcripts PTGES3-PTPRB, HMGA2-DYRK2, TMBIM4-MSRB3 were found both in the primary tumor and the metastasis examined, showing that the same clone set up these two tumor lesions." (PMID 25176350, 2014). "This is an important distinction in tumor development, and our results strengthen the argument for an Arf-independent function for Mdm2 in tumorigenesis in the absence of oncogene overexpression." (PMID 23029416, 2012). "No perturbations were found at the MDM2 locus for those samples with discordant SNP genotypes between the tumor and the germline samples." (PMID 22916154, 2012).
tumor (continued). "Our laboratory has also investigated novel and potent combinations of such MDM2 inhibitors with standard chemotherapy and demonstrated synergy with platinum drug treatments (but not gemcitabine) that resulted is tumor free survival in PDAC xenograft models." (PMID 21623005, 2011). "Ectopic PRDM5 expression significantly inhibited tumor cell clonogenicity, accompanied by the inhibition of TCF/β-catenin-dependent transcription and downregulation of CDK4, TWIST1 and MDM2 oncogenes, while knocking down of PRDM5 expression lead to increased cell proliferation." (PMID 22087297, 2011). "Survival analysis showed that positive p21/WAF1 expression or/and negative MDM2 expression in HCC was a predictor of better survival of patients after tumor resection (P < 0.05)." (PMID 20025780, 2009). "MI-63 is a novel non-peptide small molecule that has shown strong binding affinity (Ki=3 nM) for MDM2; however, its effects on paediatric cancer cells and the specific mechanism of tumour suppressor reactivation have not been evaluated." (PMID 19707204, 2009). "Several studies have found negative correlations between MDM2 tumor expression and prognosis in various cancers including breast, ovarian and brain." (PMID 19226467, 2009). "No significant reaction was seen for mdm-2: only two cases exhibited a weak positivity in 1–2% of tumor cells." (PMID 19594492, 2009).
tumor (continued). "In addition, CCND2 and MDM2 were among the most amplified genes in the cohort, both involved in the transition to the S phase of the cell cycle, suggesting the importance of this pathway in ALM pathogenesis and tumor evolution." (PMID 40362334, 2025). "Moreover, case reports describe lipomatous tumours containing areas with and without MDM2 amplification positivity." (PMID 40564858, 2025). "By targeting STAT3, BBI608 may not only sensitize cells to MDM2 inhibition but also potentially modulate the tumor microenvironment, although this was not directly assessed in our in vitro model." (PMID 40943567, 2025). "As a reference group, 37 MDM2-non-amplified tumor samples were selected." (PMID 41299419, 2025). "Although the phase III MANTRA trial of milademetan, an MDM2 inhibitor, failed to meet its primary endpoint, preclinical findings suggest that MDM2 amplification and tumor heterogeneity may contribute to resistance." (PMID 40165894, 2025). "Notably, this PROTAC may confer enhanced activity in various tumor cell types expressing MAGL and high levels of MDM2, potentially mitigating side effects in normal cells with lower expression levels." (PMID 40113745, 2025). "Immunohistochemically, the tumor cells are positive for MDM2 and CDK4 and negative for ALK." (PMID 40282503, 2025). "Similarly, neoplasms with GLI1 amplification and coamplification of MDM2/CDK4 could benefit from MDM2/CDK4 inhibitors." (PMID 38275873, 2024).
tumor (continued). "This suggests the potential use of MDM2 or CDK4 inhibitors in neoplasms where alterations in these genes do not aid the pathological diagnosis but may help identify potential therapeutic targets." (PMID 38275873, 2024). "Gli is reported to be commonly coamplified with MDM2 and CDK4, and Gli-mediated upregulation of the Hedgehog signaling pathway is enriched in dedifferentiated adipose progenitor cells and DDLPS tumor cells, resulting in undesirable immune cell infiltration of the tumor." (PMID 39723387, 2024). "Conversely, the inhibition of MDM2 up-regulates the expression of IL-15, MHC-II, and tumor necrosis factor-related apoptosis-inducing ligand receptor-1 and -2 in acute myelogenous leukemia cells and activates CD8+ T cells and NK cells, which enhances the anti-tumor effects of T cells within the TME." (PMID 39263534, 2024). "Although the actual sensitivity of stem and non-stem tumor cells to MDM2 inhibitors in patients’ tumors also remains to be investigated, possible differential sensitivity needs to be considered when interpreting the findings of ongoing trials or designing new trials." (PMID 38612758, 2024). "In the group of CAC patients, tumor infiltration by immune cells showed a positive correlation with p16 and with the glucocorticoid receptor (GR) and a negative correlation with MDM2." (PMID 37894319, 2023). "As TILs represent a considerable population in human tumor tissue and can contain a potentially large EBV-positive compartment which may be sensitive to MDM2 inhibition, more attention should be paid to the impact of tumor-associated EBV + lymphocytes on cancer biology." (PMID 36639629, 2023). "Thereafter, further in vivo rescue experiments were conducted, and our data demonstrated that the impaired potential of in vivo tumor growth triggered by NAT10 knockout could be restored by stable MDM2 overexpression, showing that MDM2 mediates the oncogenic functions of NAT10." (PMID 36609449, 2023). "Univariate analyses revealed that age, tumor location, depth and size, thick septa (> 2 mm), enhancement of septa or nodular lesions, histological findings excluding the proliferation of fibrous septa, and FISH examination for MDM2 and/or CDK4 were significantly different." (PMID 34997060, 2022). "MDM2 analysis could not be performed but CDK4 was overexpressed in both tumor components, confirming the sarcomatous nature of each and ruling out metaplasia of the fatty component." (PMID 35384584, 2022).